SYP (synaptophysin)
Diseases named in the same sentence as SYP in open-access papers (continued):
Sharing a sentence is not in itself a finding about the gene and the disease.
dementia (29 papers, 2010 to 2025). Loss of intellectual abilities interfering with an individual's social and occupational functions. "Hallmarks of AD and related dementias are accumulation of p-Tau, extra-cellular amyloid plaques, reduced synaptophysin immunoreactivity and neuronal loss." (PMID 30679733, 2019). "Moreover, double transgenic mice expressing the P301S Tau mutation together with a mutation found in familial Danish dementia showed a significant increase of Tau deposition and a significant decrease in synaptophysin levels in mouse brain." (PMID 26861879, 2016). "A reduction in the synaptophysin content of hippocampal neurons was observed after incubation with αSN, consistent with reports that a loss of synapses in the hippocampus is characteristic of the PD patients that develop dementia." (PMID 21138585, 2010). "Antibodies against the synaptic terminals—synapsin-1 and synaptophysin—are used as synaptic markers in the hippocampal complexes of AD patients and non-dementia control subjects." (PMID 35414007, 2022). "The VGLUT1, PSD95, VIAAT, som, ChAT and synaptophysin expression levels significantly decreased as dementia progressed." (PMID 29343737, 2018). "Among well studied synaptic proteins in dementia, SYP is the most abundant integral synaptic vesicle protein; its levels are often measured in attempts to quantify synapses." (PMID 22681961, 2012). "SYP, a well-studied synaptic protein in cases of dementia, is the most abundant integral synaptic vesicle protein and its levels are often measured in attempts to quantify synapses." (PMID 22681961, 2012). "This speculation is supported by evidence showing that high levels of presynaptic proteins, including synaptophysin, SNAP-25, syntaxin, and synaptobrevin, are associated with better cognitive performance and a lower risk of dementia in older adults." (PMID 40507821, 2025). "We observed lower levels of synaptophysin in AD brain homogenates and synaptoneurosomes compared with brains from age-matched controls without dementia, reflecting the known synapse loss that occurs in AD." (PMID 37652017, 2023). "Since plasma neuronal-derived exosomes levels of synaptotagmin and synaptophysin were shown to be decreased before dementia is diagnosed in patients with bvFTD50, participants at very early stages could be studied in the next future." (PMID 34373529, 2021). "Surprisingly, synaptophysin was minimally affected by the progression of dementia." (PMID 29343737, 2018). "Human studies have provided some evidence that synaptophysin may increase at an early stage in AD before decreasing as the dementia becomes more severe." (PMID 28731446, 2017). "Synaptic loss is a common hallmark of dementia, involving both specific presynaptic as well as postsynaptic proteins, which are postsynaptic density protein (PSD-95), synaptosomal-associated protein 23 (SNAP-23), synaptosomal-associated protein 25 (SNAP-25), and synaptophysin (SYP)." (PMID 38068844, 2023). "We found that the addition of αSN, but not βSN, also reduced the amount of synaptophysin in hippocampal neurons, an observation consistent with a report that the loss of synapses in the hippocampus is characteristic of the PD patients that develop dementia." (PMID 21138585, 2010). "In the present study, at the most severe stages of dementia, VGLUT1, VIAAT and synaptophysin were reduced by only 26.4%, 21.5% and 11.9%, respectively." (PMID 29343737, 2018). "Lastly, we investigated whether cortical synaptophysin and SV2A density correlated with clinical measures, including disease duration, motor-to-dementia interval and CDR scores." (PMID 38173031, 2024). "A longer motor-to-dementia interval correlated with cortical SV2A loss in PDD cases (r = -0.32, p < 0.001), but not with cortical synaptophysin loss (p > 0.05)." (PMID 38173031, 2024).
dementia (continued). "For instance, clinical and preclinical studies have shown that lower synaptophysin concentration is associated with lower cognitive scores, and a low concentration of synaptophysin is observed in patients with dementia, compared to patients without dementia." (PMID 37215178, 2023). "Finally, a reduction of Synaptophysin, a presynaptic protein that binds VAMP2 and plays a role in SNARE complex assembly and vesicle fusion, was observed to be present in FTD patients, suggesting a fundamental role of synaptic decline in dementia." (PMID 35360211, 2022). "We measured synaptophysin, PSD95, drebrin, SNAP-25, and septin 7 by ELISA in hippocampus and superior temporal gyrus from 103 adults aged <75 without dementia." (PMID 28731446, 2017). "Interestingly, pThr514 CRMP2 negatively correlated with both β-III-tubulin and synaptophysin in LBD, although for β-III-tubulin the correlations were not significant within the dementia subgroups, while correlations remained significant in DLB, but not PDD, in the case of synaptophysin." (PMID 27609071, 2016).
diabetes (28 papers, 2009 to 2025). "Another study found that long-term acetate deficiency reduced the production of synaptophysin (SYP) in the hippocampus, which impaired cognitive performances in a type 1 diabetes mellitus mice model." (PMID 37959133, 2023). "More interestingly, RORA deficiency in the amygdala completely mimicked maternal diabetes-mediated reduced synaptophysin expression and spine density in amygdala neurons." (PMID 35027651, 2022). "We found that liposomal formulation of citicoline prevents the downregulation of synaptophysin induced by diabetes, thus avoiding synapsis loss." (PMID 30127248, 2018). "In the glycyrrhizin-fed diabetic rats, the decrease in synaptophysin, tyrosine hydroxylase, and glyoxalase 1 caused by diabetes was significantly attenuated." (PMID 24733965, 2014). "In the 1,5-isoquinolinediol-treated diabetic rats, the decrease in BDNF, synaptophysin, and GS caused by diabetes was attenuated by about 50%, 34%, and 50%, respectively." (PMID 24347828, 2013). "Notably, topical treatment with liposomal formulation of citicoline was able not only to prevent the decrease of synaptophysin caused by diabetes but even to increase its expression." (PMID 30127248, 2018). "However, constant lutein (antioxidant) treatment of the STZ-induced diabetes model mice (which presented synaptophysin and BDNF reduction caused by H2O2 stimulation) suppressed decreasing of synaptophysin protein and electroretinography impairment and preserved neuronal cells survival." (PMID 26881021, 2016). "Western blot analysis confirmed that both interventions effectively reversed the diabetes-induced downregulation of synaptophysin (SYP) and PSD-95, which are key markers for evaluating synaptic integrity and plasticity." (PMID 40521191, 2025). "Western blot analysis confirmed that running exercise markedly restored the diabetes-induced downregulation of SYP and PSD-95." (PMID 40521191, 2025). "Diabetes increases the reactive oxygen species (ROS) level in cells and changes the expression of several genes, including SYP, BDNF, PAX7, and SYNCAM1, through the FOXO transcription factor." (PMID 37970442, 2023). "In the present study, we investigated the effects of diabetes on the structural damage of the cerebellum and memory-related (SYP, BDNF, PAX7, and SYNCAM1) genes." (PMID 37970442, 2023). "In the present study, we tried to investigate the effects of diabetes on the structural and functional damage of the cerebellum and memory-related genes, including SYP, BDNF, and PAX7 genes in the cerebellum." (PMID 37970442, 2023). "Proteasomal degradation of synaptophysin is a major synaptic vesicle protein in retina, it is increased due to upregulation of the angiotensin II receptors in diabetes, and contributes to neurodegeneration." (PMID 35873915, 2022). "In fact, we previously reported that pemafibrate maintained the amplitudes of OPs in a murine model of diabetes via maintaining the expression of synaptophysin, a marker of synapse." (PMID 34502311, 2021). "Another alteration detected in diabetic retina in our previous study affecting the synaptic terminals by an increase in synaptic proteins such as synaptophysin." (PMID 29420665, 2018). "Previous studies demonstrated that 1 month of diabetes decreases retinal expression of synaptophysin." (PMID 24733965, 2014). "On the other hand, diabetes induced significant downregulation of synaptophysin, TH, GS, and GLO1 in the retinas of rats." (PMID 24733965, 2014). "In the GA-fed diabetic rats, the decrease in synaptophysin, TH, GS, and GLO1 caused by diabetes was attenuated by about 58%, 55%, 79%, and 53%, respectively." (PMID 24733965, 2014). "Despite the preservation of RCG number, a decrease in synaptophysin immunoreactivity was observed in the retinal IPL from diabetic animals housed in SE at early stages of diabetes (i.e., 6 weeks after STZ injection), in agreement with other reports." (PMID 25004165, 2014).
diabetes (continued). "EE housing significantly prevented the decrease in synaptophysin immunoreactivity induced by diabetes, supporting a preservation of synaptic connections between inner retinal neurons." (PMID 25004165, 2014). "EE housing prevented the effect of experimental diabetes on synaptophysin immunoreactivity in the IPL." (PMID 25004165, 2014). "In the present study, we demonstrated that, similar to diabetes, HMGB1 caused a significant decrease in the synaptic vesicle protein synaptophysin and a significant increase in the activated cleaved caspase-3 in the retina of normal rats." (PMID 23766563, 2013). "Increases in synaptophysin mRNA translation in the retina after diabetes prompted an investigation into synaptophysin glycosylation." (PMID 22970294, 2012). "Newly synthesized synaptophysin degradation was significantly accelerated in the retina after 1 and 2 months of diabetes compared to controls (p<0.05)." (PMID 22970294, 2012). "Since the relative mRNA content of synaptophysin was unchanged after 1 month of diabetes, the mRNA translation, protein glycosylation and degradation in the retina were identified as potential molecular mechanisms for the reduction." (PMID 22970294, 2012). "Together, these data suggest that the previously reported reduction in synaptophysin in the rat retina due to diabetes is attributable to dysregulation of post-translational processing." (PMID 22970294, 2012). "Diabetes significantly depleted the newly synthesized 35S-synaptophysin compared to controls, offering a potential explanation." (PMID 22970294, 2012). "Immunoblot analysis indicated that after 1 month of STZ-diabetes several presynaptic proteins, including synaptophysin, were significantly reduced in the rat retina compared to age-matched controls." (PMID 22970294, 2012). "Evidently, while total mRNA translation in the retina eventually stabilizes after the induction of diabetes, synaptophysin mRNA translation continues at a higher rate." (PMID 22970294, 2012). "In conclusion, the data presented in this study suggest that synaptophysin turnover and post-translational processing in the rat retina is compromised by experimental diabetes." (PMID 22970294, 2012). "The total amount of synaptophysin was reduced by diabetes while the mRNA translation of newly synthesized 35S-synaptophysin was elevated." (PMID 22970294, 2012). "Previous data showed that STZ-diabetes significantly reduced the content and immunoreactivity of inner and outer plexiform layer synaptophysin, and several other synaptic proteins in the rat retina." (PMID 22970294, 2012). "In this study, we report that “immature” glycosylated synaptophysin was significantly increased in rat retinas after 1 month of STZ-diabetes compared to age-matched controls." (PMID 22970294, 2012). "A recent study reported that 1 month of STZ-diabetes decreased the size and density of synaptophysin-immunoreactive puncta in both retinal plexiform layers." (PMID 22970294, 2012). "In the present study on rat retinas, STZ-diabetes significantly increased synaptophysin mRNA translation compared to age-matched controls." (PMID 22970294, 2012). "The results suggest that diabetes increases the mRNA translation of synaptophysin while its post-translational glycosylation is increased, and its degradation is accelerated." (PMID 22970294, 2012). "Furthermore, hippocampal synapse-associated proteins, including synaptophysin and PSD95, are suppressed in diabetes." (PMID 38421831, 2024). "The results showed that maternal diabetes (CTL/WT) significantly decreased SYP expression, including mRNA and protein levels, as well as spine density, compared to the control (CTL/WT) group, and prenatal RORA deficiency (RORA−/−) treatment mimicked this effect." (PMID 35027651, 2022). "Interestingly, 3TC treatment significantly reduced diabetes-induced amacrine death and synaptophysin reduction." (PMID 31035433, 2019).
diabetes (continued). "We found a downregulation in synaptophysin in retinas from diabetic mice treated with vehicle in comparison with non-diabetic mice, thus revealing a synapse loss induced by diabetes." (PMID 30127248, 2018). "Moreover, a previous study also documented that inhibition of ERK activation in the retina by lutein blocks the actions of diabetes that cause BDNF depletion and synaptophysin reduction." (PMID 24347828, 2013). "This diabetes-induced irregularity in post-translational processing could explain the accelerated degradation of retinal synaptophysin in diabetes." (PMID 22970294, 2012). "This study tested the hypothesis that STZ-diabetes alters synaptophysin protein turnover and glycosylation in the rat retina." (PMID 22970294, 2012). "Diabetes likely increases mannose rich glycosylated synaptophysin content in the retina." (PMID 22970294, 2012). "It was hypothesized that STZ-diabetes alters synaptophysin mRNA translation and N-glycosylation in the rat retina." (PMID 22970294, 2012). "Moreover, AT1R reduced synaptophysin expression in a posttranscriptional fashion in the retina of the diabetes model mice." (PMID 22144984, 2011). "However, in a HFD-induced diabetes setting, eyes treated with si-Tau displayed significantly reduced immunoreactivity for total and phosphorylated tau, accompanied by distinctly increased expression of synaptophysin, as compared with si-sc control." (PMID 30466464, 2018). "Interestingly, we found that caffeine prevented the diabetes-induced loss of SNAP25 but not of synaptophysin." (PMID 30686981, 2018). "Diabetes-induced changes in neuronal-specific class III tubulin (Tuj-1), synaptophysin, glutamine synthetase, and vimentin were attenuated in response to SMOX inhibition." (PMID 39768141, 2024). "The role of SYP, BDNF, and PAX7 in memory and the effect of diabetes on the reduction of these genes have been reported in several studies." (PMID 37970442, 2023). "The main mechanism implicated in these beneficial effects were the inhibition of the downregulation of synaptophysin and its anti-inflammatory properties by means of preventing the upregulation of NF-κB and TNF-α (Tumor Necrosis Factor α) induced by diabetes." (PMID 30127248, 2018). "The HMGB1 inhibitor GA attenuated diabetes-induced upregulation of HMGB1 protein and mRNA; cleaved caspase-3 and glutamate; and downregulation of synaptophysin, TH, GS, and GLO1 in the retinas of rats." (PMID 24733965, 2014). "Western blot analysis was used to assess the effect of GA on diabetes-induced alterations of HMGB1, ERK1/2 activation, cleaved caspase-3, synaptophysin, TH, GS, and GLO1." (PMID 24733965, 2014). "Administration of PARP inhibitor to diabetic rats significantly attenuated diabetes-induced increased expressions of PARP activation, ROS, p-ERK1/2, and cleaved caspase-3 and decreased BDNF, synaptophysin, and GS levels in the retinas." (PMID 24347828, 2013). "In conclusion, these data suggest that PARP activation mediates diabetes-induced increased oxidative stress, downregulation of BDNF, synaptophysin, and GS, and upregulation of caspase-3." (PMID 24347828, 2013). "Western blot analysis was used to assess the effect of 1,5-isoquinolinediol on diabetes-induced alterations of p-ERK1/2, BDNF, synaptophysin, GS, cleaved caspase-3, and ROS." (PMID 24347828, 2013). "We found that PARP inhibition by 1,5-isoquinolinediol significantly prevented the diabetes-induced downregulation in BDNF, synaptophysin, and GS and upregulation of cleaved caspase-3 expressions." (PMID 24347828, 2013). "On the other hand, diabetes induced significant downregulation of the neurotrophin BDNF, the synaptic function marker synaptophysin, and GS." (PMID 24347828, 2013). "In conclusion, these data suggest that diabetes-induced increased oxidative stress, downregulation of BDNF and synaptophysin, and upregulation of cleaved caspase-3 were also induced by HMGB1." (PMID 23766563, 2013).